CXCR4 (C-X-C motif chemokine receptor 4)
Diseases named in the same sentence as CXCR4 in open-access papers (continued):
Sharing a sentence is not in itself a finding about the gene and the disease.
tumor (continued). "On the one hand, it induced cancer stem cells phenotype via CXCR4-mediated PKCα/NF-қB activation, ultimately increasing the number of disseminated tumor cells in the soft and bone tissues." (PMID 37497001, 2023). "Subsequently, by inhibiting NOTCH1, the repression of CXCR4 resulted in a reduction in tumor growth." (PMID 37833915, 2023). "SDF-1, currently known as CXCL12, directly binds to its receptor CXCR4, a G-protein-coupled receptor, to induce tumor angiogenesis, thereby promoting breast cancer growth." (PMID 37496657, 2023). "Our laboratory has previously shown in a rhabdomyosarcoma animal model that targeting CXCR4 with a monoclonal antibody in combination with activated and expanded NK-cell therapy prevented lung metastasis and tumor implantation." (PMID 37176035, 2023). "An analysis of the AS events of CXCL12 and CXCR4 transcripts between multiple tumor and normal tissues suggested divergent expression of CCL12- or CXCR4-SVs in tumor tissues." (PMID 37198402, 2023). "Among various flavonoids, curcumin has been extensively studied in terms of cancer therapy owing to its diverse functions, which include inhibition of the CXCL12/CXCR4 axis, resulting in suppressed tumor metastasis." (PMID 38004606, 2023). "Genomic characterization of WM tumor cells has identified recurrent somatic mutations in MYD88 (>95% patients) and CXCR4 (>30% patients) genes, and deletions involving chromosome 6q (del6q; ∼50% patients), among other alterations." (PMID 37493341, 2023). "The CXCL12/CXCR4 axis plays a pivotal role in tumor development, survival, angiogenesis, metastasis, and tumor microenvironment." (PMID 37511481, 2023). "These authors utilized the novel CXCR4 inhibitor Peptide R for therapeutic purposes, which decreased cancer cells’ metastatic potential by impairing the crosstalk between tumor cells and normal stem cells." (PMID 37176108, 2023). "For Metascape analysis, we specifically selected genes from the top 200 gene list, which were overexpressed—having a significant higher mean expression according to Kruskal–Wallis test—in CXCR4 high-expressing tumor samples." (PMID 36672341, 2023). "In cancer CCR7 is upregulated together with CXCR4, and the dimer formed by both can activate signaling pathways and promote tumor metastasis." (PMID 37864213, 2023). "For example, cAMP-mediated signaling is typically involved in the regulation of heart function; CXCR4 signaling contributes to tumor growth and invasion." (PMID 37550674, 2023). "High levels of CXCL12 in the tumor can attract CXCR4-expressing immune cells, fibroblasts and endothelial cells to the tumor site further promote tumor growth." (PMID 38022679, 2023). "PTHrP ablation leads to a significant decrease in tumor growth and metastasis as well as the reduced expression of several factors known to support tumor progression, including: CXCR4, Ki67, Bcl-2, AKT1, and Cyclin D1." (PMID 38435029, 2023). "The CXCL12/CXCR4 axis is a key mediator of tumor spread, site-specific metastasis, and patient survival." (PMID 37227446, 2023). "Within the TME, the tumor homing of mesenchymal stromal cells is regulated by the MIF-(CD74 + CXCR4) ligand–receptor pair in the MIF pathway." (PMID 37874419, 2023). "Tumor growth, metastasis, angiogenesis, relapse and therapeutic resistance have been correlated with an overexpression of CXCR4." (PMID 37376181, 2023). "Researchers introduced multiple CXCL12/CXCR4 inhibitors and antagonists to observe its effect on tumor development." (PMID 38313431, 2023). "PMVs can interact with tumor cells as well as circulating immune cells via receptors such as CXCR4, which aids in the growth and spread of tumors, and GPIIb/IIIa, which enhances tumor survival and migration." (PMID 37958838, 2023). "As shown in the literature, MSLN and CXCR4 are potential agents for targeted anti-tumour or endo-radioligand therapy." (PMID 37047331, 2023).
tumor (continued). "CXCL12, secreted by tumor and stromal cells, regulates plasmacytoid DC trafficking to tumors and integrin α5 and C-X-C Motif Chemokine Receptor 4 (CXCR4) expressed by plasmacytoid DCs and promotes tumor clearance through antigen presentation." (PMID 37895310, 2023). "BL-8040, a high-affinity CXCR4 antagonist, was able to prevent tumor growth and reduce tumor survival cells." (PMID 36980182, 2023). "Since CXCR4 plays a central role in tumor progression, angiogenesis, metastasis, and cell survival, its malfunction is directly associated with various forms of cancer, where generally it is not only overexpressed but also overactivated." (PMID 36901829, 2023). "In u87.CXCR4 tumor xenografted SCID mice, both Al18F-tracers demonstrated an elevated accumulation in the liver, spleen and bone marrow, however, the tumor uptake remained comparably low." (PMID 37318633, 2023). "Focusing exclusively on tumor tissues of PDAC patients, we evaluated the role of the CXCR4 expression in tumor stroma with respect to prognostic factors, finding a relationship between poor differentiation and high CXCR4 expression." (PMID 37697316, 2023). "Applying RF learning to transcriptomic data of 29 cancer entities, we identified the top 200 gene signatures, which were most discriminative regarding CXCR4/FAP high- vs. low-expressing tumor samples." (PMID 36672341, 2023). "Inhibitors of the CXCR4–CXCL12 axis have been developed as a therapeutic approach considering the prognostic relevance of CXCR4 overexpression and the role of this axis in tumor growth (AMD3100/Plerixafor, Nox-A12 and others)." (PMID 36982302, 2023). "For example, overexpression of the CXCR4 on the surface of MSC cells clearly increases their ability to migrate toward tumor sites by SDF1 alpha release." (PMID 38004925, 2023). "In a paracrine manner, CXCL12 attracts CXCR4-expressing tumour cells to a new tumour niche, resulting in tumour cell invasion and metastasis." (PMID 37509322, 2023). "Knockdown of CXCR4 sensitized the tumor cells to trastuzumab in two-line co-culture, suggesting CXCR4 plays a role in the function of trastuzumab by interrupting HER2 oncogenic signals." (PMID 37280713, 2023). "This brings an advantage to treatment with [177Lu]Lu-Pentixather, as it can be directed at tumor cells and neovasculature when CXCR4 is present." (PMID 33550492, 2022). "In this regard, an increasing number of CXCR4( +)/SSTR( −) metastases were identified in patients with increasing tumor aggressiveness." (PMID 35674738, 2022). "Plerixafor, an exogenous CXCR4 antagonist with high binding affinity, can disrupt adhesive tumor-stroma interactions and achieve treatment goals." (PMID 36091426, 2022). "Meanwhile, CXCL12 expression in tumor promoted the recruitment of CXCR4-expressing immune cells to potentiate the tumor-promoting effect." (PMID 35729596, 2022). "For example, the expression of CXCR4 will increase significantly from T2 tumor stage to T3 tumor stage (P = 0.028)." (PMID 35768705, 2022). "Bone-homing tumor cells tend to overexpress chemokine receptors, CXCR4, CXCR6, and CXCR2 that subsequently contribute to the movement of the tumor cells from the bone marrow to other organs by seeking CXCL12, CXCL-16, and CXCL-10 respectively." (PMID 35399952, 2022). "Studies performed on patient-derived tumor tissue showed that high CXCR4 expression correlates with the presence of more advanced and higher-grade tumors." (PMID 36077755, 2022). "Our study is the first to examine the expression of FOXP3, CD8, and CXCR4/FOXP3 in conjunction with tumor progression and prognosis in patients with conjunctival SCC." (PMID 35358193, 2022). "In contrast, our [111In]G5-Ctrl control dendrimers with size averaging around 8 nm showed significantly longer circulation and substantial passive tumor accumulation, reaching 10.06 ± 1.46%ID/g at 48 h after injection in U87-stb-CXCR4 and U87 tumors." (PMID 35336029, 2022).
tumor (continued). "The SDF-1α/CXCR4 axis has been reported to play an important part in the modulation of many responses, including chemotaxis, tumor growth, migration and distant metastasis." (PMID 35453553, 2022). "The CXCL12/CXCR4 biological axis is also closely related to tumor angiogenesis, and blocking this axis can inhibit tumor angiogenesis either by inhibiting VEGF or directly." (PMID 35770088, 2022). "CXCR4 plays a crucial role in the process of neoangiogenesis and migration of metastatic tumor cells." (PMID 35877436, 2022). "To summarize, these data show consistent effects of CAFs on the downregulation of CXCR3 and the upregulation of CXCR4 expression on T cells in both 2D and 3D cultures, as well as when tumor spheroids were present in the 3D cultures." (PMID 35954489, 2022). "The detection of these CXCR4+ tumor cells in the invasive front of the primary tumors exhorted us to investigate the potential anti-invasive effect of the T22-DITOX-H6 nanotoxin." (PMID 35456719, 2022). "The stromal cell-derived factor-1 (CXCL12) activates CXC chemokine receptor-4 (CXCR4) and promotes tumor cell migration as well as invasion." (PMID 35910383, 2022). "One hour after i.v. injection with Luciferase-expressing fibrocytes, ESCC tumor-bearing mice were treated with CXCR4 neutralizing antibody, PBS or IgG, respectively." (PMID 35941662, 2022). "The adhesion of MCL tumor cells to stromal cells is attributed in part to the high level of expression of functional CXCR4, CXCR5 chemokine receptors, and VLA-4 adhesion molecules on the surface of MCL." (PMID 35804999, 2022). "Twenty-two of forty-three patients showed a high CXCR4 expression, while 21 of 43 patients showed a low CXCR4 tumor expression in recurrent cancer biopsies in the overall cohort." (PMID 35397601, 2022). "Conversely, as expected, the mean tumor volume of mice in the CXCR4/SKOV3 group was significantly increased at days 10, 13, 15 and 19 compared with the Scramble/SKOV3 group." (PMID 35681259, 2022). "We further performed immunofluorescence staining on hepatic UM metastases to analyze the spatial relationship of CXCR4 expression and tumor cells." (PMID 35145271, 2022). "The resulting CX43/CXCL12/CXCR4 interaction boosted mitochondrial trafficking in MSCs and protected tumor cells from the effects of anti-myeloma drugs." (PMID 35958625, 2022). "BsNb PX4 decreased the viability of CXCR4-expressing tumour cell lines, including Jurkat cells, AsPC-1 cells and Panc-1 cells, in a dose-dependent manner." (PMID 36284271, 2022). "CXCL12 produced by CAFs recruits CXCR4-expressing endothelial progenitor cells and immune suppressive Tregs, which contributes to angiogenesis and tumor growth." (PMID 36010899, 2022). "Tumors were divided in two groups according to median of ESA+CD24+CD44+ or CXCR4+CD133+ cell percentage [high stemness tumor (HST) > median, low stemness tumor (LST) ≤ median]." (PMID 36142575, 2022). "CXCR4 antibodies can disrupt adhesive tumour/stroma interactions and mobilize cancer cells from their protective stromal microenvironment, making them more accessible to chemotherapeutic agents." (PMID 35008410, 2022). "For example, chemokine receptor type 4 (CXCR4) is a class of G-protein-coupled receptor that plays an important part in tumor metastasis by gathering tumor cells along chemokine gradients." (PMID 36096856, 2022). "Pharmacological agents targeting the CXCR4/CXCL12 axis were developed to inhibit tumor growth and metastasis and also mobilize hematopoietic stem cells to the periphery for subsequent transplantation." (PMID 33603130, 2022). "In the various populations of TICs/TACs, CXCR4 expression was examined to evaluate if a relationship exists between the aggressiveness of the tumor and their numbers in the blood stream." (PMID 35259193, 2022). "Like CXCR2 inhibition, targeting CXCR4 represents a different strategy to reduce tumor recruitment and neutrophil mobilization from the BM." (PMID 35664746, 2022).
tumor (continued). "The CXCR4+ vimentin+ cells were observed in the tumor budding in the primary tumor margin, demonstrating that the CXCR4+ cells previously identified by IHC were indeed human cancer cells (vimentin+)." (PMID 35456719, 2022). "As in the whole-block MTC samples, the extent of SST and CXCR4 expression in the TMA tumour samples was very low overall." (PMID 35799158, 2022). "Further analysis showed that ligand-receptor pairs, including MIF − (CD74 + CXCR4), MIF − (CD74 + CD44), MDK–NCL and LGALS9 − CD45, etc. mediated the communication between m6A associated subtypes of TME cells and tumor epithelial cells." (PMID 35509079, 2022). "AMD3100, Peptide R, CPZ1344, and AMD3465 are inhibitors for CXCR4 that reduce tumor growth and inhibit GBM cell invasiveness and migration." (PMID 35745762, 2022). "CXCR4 expression forms an integral part of tumour survival and spread in several solid malignancies, and its expression is generally associated with more aggressive cancers, a poorer prognosis and high potential for metastases and/or recurrence." (PMID 36140541, 2022). "Our results demonstrate that while CXCR4 targeting is beneficial for tumor accumulation at early time points, differences in tumor uptake are diminished over time as passive accumulation takes place." (PMID 35336029, 2022). "The C-X-C chemokine receptor 4 (CXCR4) has been suggested to play an important role in several types of cancers and is related to biological behaviors connected with tumor progression." (PMID 35729596, 2022). "The CXCL12/CXCR4 axis plays a pivotal role in tumor development, survival, angiogenesis, metastasis, and the tumor microenvironment." (PMID 35628268, 2022). "Some studies also found that the ability of CXCR4 to regulate neovasculature is accountable for addressing tumor cell metastasis, especially in solid organs." (PMID 36816176, 2022). "Further, treatment of fresh human PDAC specimens with PD-1 and CXCR4 inhibitors gave rise to enhanced tumor cell death and also lymphocyte expansion." (PMID 34980128, 2022). "Overall, our comprehensive analysis identified novel PCa TEC targets and highlights CXCR4/CXCL12 interaction as a potential novel target to interfere with tumor angiogenesis in PCa." (PMID 35717322, 2022). "Certain proteins expressed on the surface of tumor cell membranes, such as PD-L1 and CXCR4, are known to help nanoparticles evade the immune system." (PMID 36461108, 2022). "Binding of CXCL12 to CXCR4 on tumor cells can inhibit the apoptosis of tumor cells and promote the epithelial-to-mesenchymal transition." (PMID 35169832, 2022). "Consistent with outcome of the survival analysis, CXCR4 was significantly upregulated in GC patients with younger ages and worse tumor status, including the grade 3 (p = 0.0062) and M1 stage, than in patients with other tumor statuses (p = 0.0194)." (PMID 36173625, 2022). "Patients with a high dichotomized distribution of CXCR4 positive tumor cells had a significantly higher 6-month RFS rate (p = 0.018)." (PMID 35397601, 2022). "The results showed the upregulation of RANK-L, RANK, OPN, CXCR4, RUNX2 and FLT1 and the downregulation of OPG and CXCL12 genes, underlining their involvement and promising role in these neoplasms." (PMID 35203581, 2022). "The CXCR4/CXCL12 axis plays a relevant role in shaping the tumor microenvironment (TME), mainly towards dampening immune responses." (PMID 35565443, 2022). "Two major strategies to target CXCR4 are direct inhibition and combination agents, aiming to induce cell death in CXCR4 + tumor cells." (PMID 35303910, 2022). "CXCR4 also contributes to angiogenesis, metastasis, tumor growth and invasion, even relapse and therapeutic resistance in some cancers." (PMID 36816176, 2022).
tumor (continued). "As we have already indicated, tumor-infiltrating pDCs were significantly increased in the TME and were associated with tumor size and lymph node metastasis via the TNF-α/NF-κB/CXCR-4 pathway in OSCCs." (PMID 35740551, 2022). "Tumor expressing high levels of CXCL12 repelled CXCR4-expressing T cells and evaded an anti-tumor response." (PMID 33603130, 2022). "Strikingly, CXCR4 overexpression markedly abolished the effect of PTX on reducing tumor size (*P<0.05)." (PMID 35681259, 2022). "These CXCR4+ cancer cells, located in the tumor front, are empowered with a greater invasive and metastatic potential, and have also been described in other cancer types, in which they have been identified as cancer stem cells (CSCs)." (PMID 35456719, 2022). "In GC tissues, CXCL12/CXCR4, highly overexpressed, is tightly correlated with the metastasis of lymph nodes, higher tumor, node, metastasis staging, and poor prognosis." (PMID 35647303, 2022). "CXCL12, the chemokine binding to the CXCR4, is secreted from fibroblast cells in the tumor microenvironment." (PMID 35638450, 2022). "The inhibited expression of CXCR4 is one of the significant factors in tumor regression promoted by TNFR deletion." (PMID 36358977, 2022). "C-X-C motif chemokine receptor 4 (CXCR4) is involved in migration of tumor cells and angiogenesis in various solid cancers." (PMID 35312939, 2022). "The transdifferentiation of GSCs into pericyte-like cells has been described to rely on the recruitment of GSCs by tumor endothelial cells via SDF-1/CXCR4 signaling and the generation of pericytes through the activation of the TGF-β pathway." (PMID 36294763, 2022). "The CXCL12/CXCR4 axis represents one of the most intensively studied pathways in the tumor tropism of MSCs." (PMID 36324128, 2022). "Both nanotoxins, but especially T22-DITOX-H6 at a higher degree, reduce tumor growth and prolong animal survival after their repeated administration in a subcutaneous CXCR4+ EC model." (PMID 36612081, 2022). "In a Panc02 subcutaneous tumor mouse model, CXCR4 antagonist BL-8040 combined with anti-PD-1 and irinotecan, fluorouracil and leucovorin reduced tumor growth by 58% compared with chemotherapy alone." (PMID 35139879, 2022). "CXCL12 is secreted by CAFs and coats PDAC tumor cells, since the malignant cells express higher levels of CXCR4 compared to normal pancreas tissue." (PMID 36077755, 2022). "Most importantly, CXCR4 knockdown synergistically enhanced the effect of PTX on inhibiting tumor growth (*P<0.05)." (PMID 35681259, 2022). "Cancer progression gene array and immunohistochemical analyses of FOXP3 as a Treg marker, CD8 as a tumor-infiltrating lymphocyte marker, and CXCR4 expression on activated Tregs were conducted in a series of 31 conjunctival SCC cases." (PMID 35358193, 2022). "Both CXCR4-targeted and control dendrimers showed similar long circulation times and a degree of passive tumor accumulation." (PMID 35336029, 2022). "The IL-6/JAK2/STAT3 pathway and CXCL12/CXCR4 interactions between tumor cells and CAFs were enriched." (PMID 35784460, 2022). "The CXCL12/CXCR4 axis is a classic signaling that governs the homing of MSCs and upregulates the expression of PD-L1 to mediate selective immunosuppression within a tumor." (PMID 36324128, 2022). "Staining patterns of FOXP3, CD8, and CXCR4 were examined separately between tumor cells and stromal cells in SCC tumors." (PMID 35358193, 2022). "In order to confirm these observations, CXCR4 and human vimentin co-immunofluorescent staining was performed on the tumor samples." (PMID 35456719, 2022). "Treatment of fresh human PDA slice cultures with a combination of PD-1 and CXCR4 blockade had an anti-tumor effect with concomitant peripheral CD8+ T cell expansion." (PMID 36077755, 2022). "CXCR4 is not only expressed by cancer cells themselves, but also by tumour-infiltrating immune cells." (PMID 36140541, 2022).